IL6 (interleukin 6)
Diseases named in the same sentence as IL6 in open-access papers (continued):
Sharing a sentence is not in itself a finding about the gene and the disease.
Abdominal obesity (continued). "However, a study comparing EPA (2.7 g) and DHA (2.7 g) in individuals with abdominal obesity and low-grade systemic inflammation found lowering of CRP, IL-6, IL-18, and TNF, where DHA was more potent than EPA." (PMID 40058591, 2025). "Furthermore, most patients had abdominal obesity, with significantly higher body mass index (BMI), waist-to-hip ratio (WHR), waist-to-height ratio (WHtR), fat percentage and IL-6 levels." (PMID 32168955, 2020). "Although abdominal obese women had higher C-reactive protein and fibrinogen plasma levels at the baseline, these are not good markers of abdominal obesity such as IL-6, TNF-α, and TNF-β." (PMID 30107482, 2019). "The main effect of central obesity was observed in insulin, PAI-1, chemerin and IL-6." (PMID 30114249, 2018). "Subjects with abdominal obesity (waist circumference ≥ 85 cm) showed higher serum hs-CRP and IL-6 levels and a lower adiponectin level than those without abdominal obesity." (PMID 17903275, 2007). "It has been proposed that in central obesity, white adipose tissue is infiltrated by activated macrophages (M1) and correlates with secreting monocyte chemoattractant protein-1 (MCP-1), tumor necrosis factor α (TNFα), interleukin-1β (IL-1β), interleukin 6 (IL-6), and interleukin 1α (IL-1α)." (PMID 40002817, 2025). "Individuals with abdominal obesity often exhibit high levels ofproinflammatory cytokines (tumor necrosis factor-α (TNF-α), interleukin-1α (IL-1α), interleukin-1β (IL-1β), interleukin-6 (IL-6)and interleukin-8 (IL-8)), which can be considered significant prognostic indicators of CVD risk." (PMID 39076338, 2024). "Previous studies have highlighted that visceral adipose tissue produces large amounts of interleukin-6 (IL-6), which promotes the secretion of acute-phase proteins such as C-reactive protein (CRP), and thus the levels of IL-6 and CRP are significantly increased in individuals with abdominal obesity." (PMID 38287292, 2024). "Studies have shown that central obesity/VAT is related to dysregulated adipokine secretion, with increased levels of plasminogen activator inhibitor (PAI-1), tumor necrosis factor-alpha (TNF-α), monocyte chemotactic protein-1 (MCP-1), angiotensinogen, and interleukin 6 (IL-6)." (PMID 35276815, 2022). "We hypothesized that habitual dietary fat intake, the IL6 genotype, and MED or the CED for 16 weeks would affect selected biomarkers of inflammation (TNFα and IL6) in postmenopausal women with central obesity; the obtained results partly confirm this hypothesis." (PMID 31295854, 2019). "Abdominal obesity promotes increased secretion of a range of metabolites and of biologically active substances, including glycerol, FFA, inflammatory mediators (e.g. tumor necrosis factor alpha (TNFα) and interleukin-6 (IL-6)), plasminogen activator inhibitor-1 (PAI-1) and C-reactive protein." (PMID 24410812, 2014). "Looking specifically at central obesity, higher levels of IL-5, IL-6, IL-12, IL-13, and IFN-γ were reported in participants with abdominal obesity compared to those without." (PMID 36364892, 2022). "Abdominal obesity group presented significantly higher hs-CRP and IL-6 levels, and a lower adiponectin level than non-abdominal obesity group." (PMID 17903275, 2007). "When abdominal obesity was absent, inflammatory proteins, such as hs-CRP and IL-6, did not increase significantly with clustering of MetS components, despite the fact that previous studies found an association between CRP and MetS." (PMID 17903275, 2007). "However, our findings were not completely in agreement with these previous works; the presence of central obesity in our non-MetS subjects could not lead to significantly elevate serum levels of CRP and IL-6." (PMID 29670915, 2018).
kidney damage (130 papers, 2010 to 2026). "Previous studies have implicated the JAK2/STAT3 signaling pathway and downstream IL-6 in uric acid-induced kidney injury, highlighting potential strategies for preventing and treating hyperuricemia-associated kidney damage." (PMID 40170729, 2025). "Aging-associated kidney damage has been linked to upregulated endothelin A receptor, interleukin-6, and NADPH oxidase 2 expression as well as the generation of superoxide and downregulation of klotho, the ET B receptor, and manganese superoxide dismutase." (PMID 37507979, 2023). "We have shown that serum levels of insulin like growth factor binding proteins (IGFBP), TNF-α and IL-6 pathways were able to stratify T1D patients into risk categories for a number of complications, including nephropathy and retinopathy." (PMID 33868296, 2021). "Regarding the association between IL-6 and histologic kidney damage, experiments in mice have shown that IL-6 promotes glomerular hypertrophy and mesangial proliferation." (PMID 33155543, 2021). "IL6 encodes for interleukin-6, which has been shown to induce a cellular-mediated immune reaction that causes kidney damage." (PMID 34300206, 2021). "High levels of IL-6 have been associated with kidney damage in humans and in a number of animal models." (PMID 26583155, 2015). "Studies have found that CKD patients often exhibit T-cell exhaustion and impaired neutrophil chemotaxis, resulting in a persistent low-grade inflammatory state (e.g., elevated IL-6) while simultaneously increasing the risk of infections, which further accelerates kidney damage." (PMID 41598767, 2026). "Tocilizumab was started, and not only the MCD-related extra kidney lesions, but also the nephropathy improved, suggesting that IL-6 may be the etiologic agent of AA amyloid associated with the high inflammatory state in MCD." (PMID 39776937, 2024). "As a case in point, a study has shown that monocyte chemoattractant protein-1 (MCP-1) could stimulate the synthesis and release of TNF-α and IL-6 in renal cells, initiate programmed inflammation and further cause kidney damage." (PMID 35054932, 2022). "For example, Chang suggested that IL-6 gene polymorphisms rs1800796 and rs1524107 might serve as predictors of progression of nephropathy in Chinese T2DM." (PMID 33016995, 2020). "Acute nephrotoxicity is closely related to inflammatory response and induces the expression of various cytokines and chemokines, and elevated cytokine levels (such as tumor necrosis factor (TNF)-α, interleukin (IL)-1β, and IL-6) are associated with kidney damage." (PMID 32916975, 2020). "Interleukin-6 (IL-6) is also implicated in manifestations of nephropathy." (PMID 25520922, 2014). "Pro-inflammatory cytokines (TNF-α, IL-6) enhance metabolic stress, leading to progressive kidney damage." (PMID 40698245, 2025). "In the context of DKD, IL-6 serves as a promising early marker of kidney damage, reflecting systemic inflammatory activity and early renal dysfunction rather than direct podocyte injury." (PMID 41145267, 2025). "Studies have shown that TNF-α and IL-6 are involved in the pathogenesis of LN, promoting inflammatory responses and exacerbating kidney damage." (PMID 40573311, 2025). "Among the various inflammatory mediators, pro-inflammatory cytokines, such as interleukin-1β (IL-1β) and interleukin-6 (IL-6), are involved in the development and progression of nephropathy." (PMID 41009007, 2025). "The study found that WIT effectively reduced renal MPO activity and NF-kB, IL-1β, TNF-α, and IL-6 levels in DOX-induced kidney damage." (PMID 40006061, 2025). "The elevated urinary levels of IL-6 and N-Gal in these patients support a link between mechanical stress, inflammation, and kidney damage." (PMID 40283616, 2025). "Elevated IL-6 levels promote ROS and inflammatory markers, leading to cellular damage and complications like nephropathy, retinopathy, and cardiovascular diseases." (PMID 39857603, 2024).
kidney damage (continued). "DKD adds the kidney as another major site of IL-6 production, since the extent of kidney damage appears to correlate with increased renal IL-6 mRNA expression in DKD patients." (PMID 39723211, 2024). "Elevated interleukin-6 (IL-6) levels further intensify inflammation and oxidative stress, disrupting insulin signaling and worsening complications such as nephropathy, retinopathy, and neuropathy." (PMID 39857603, 2024). "Proinflammatory cytokines, including IL-1β, TNF-α, and IL-6, are mediators of kidney injury, and the downregulation of inflammatory cytokines supported strain 44XBT-induced alleviation of kidney damage." (PMID 38814072, 2024). "As the concentration of IL-6 rises in diabetic patients with nephropathy, this study suggests that IL-6 plays a significant role in the development and progression of DN." (PMID 39280507, 2024). "Pre-clinical models show that in nephrotoxin-induced AKI, IL-6 expression is enhanced more than a hundred-fold in the kidneys, mainly in the renal tubular epithelial cells; it is also strongly correlated with kidney damage." (PMID 36986882, 2023). "Nevertheless, the role of IL-6 in the evolution of kidney damage, determined through its serum levels, seems to be different in the acute and recovery phases." (PMID 36837598, 2023). "In contrast, cardiac mRNA expression of IL-6 was only slightly increased in NZB/W mice with severe kidney damage." (PMID 37554366, 2023). "Low levels of IL-6 in the group with the greatest kidney damage is consistent with the idea that IL-6 is essential to the recovery process of that organ." (PMID 36837598, 2023). "To prove that fucoidan nanoparticles are involved in regulating inflammatory cytokines in streptozotocin-induced kidney damage in diabetic rats, we measured the inflammatory cytokines level of IL-6 and TNF-α." (PMID 35685736, 2022). "This was also confirmed by other literature reports, which indicated that the functional and structural abnormalities in the course of DN and the progression of kidney damage are related to IL-6." (PMID 35054831, 2022). "One of the most common interleukins recurring in selected nephropathies are the proinflammatory interleukins IL-6 and IL-18." (PMID 35054831, 2022). "PFD treatment significantly inhibited the expression of TNF-α, IL-6, and nitric oxide synthase-2 by M1 macrophages, suggesting its efficacy in the early and late periods of kidney damage." (PMID 33520317, 2021). "The treatment with BA at 10 and 30 mg/kg can restore the imbalance of inflammatory mediators (tumor necrosis factor alpha (TNF-α), interleukin 6 (IL-6), and IL-10) and prevent cecal ligation and puncture-induced kidney damage in mice." (PMID 34721992, 2021). "IL-6 and cystatin-C, as markers of inflammation and kidney damage, respectively, are likely to provide insight into prediction of risk for CKD outcomes after AKI, as our feasibility data suggest that IL-6 is a more sensitive than high sensitivity-CRP." (PMID 30898807, 2019). "Three inflammatory mediators in particular: interleukin 6 (IL-6), tumor necrosis factor α (TNF-α), and C-reactive protein (CRP), when combined in a z-score, are associated with development of retinopathy, nephropathy and cardiovascular disease in diabetics." (PMID 29075511, 2017). "On the basis of these findings, we next examined the in vivo effect of hyper‐IL‐6 in the model of chronic folic acid‐induced nephropathy (the duration of this model allows for the delayed institution of treatments)." (PMID 28297566, 2017). "Preconditioning with 2 g/kg montelukast significantly attenuated hepatic tissue injury and kidney damage, and decreased plasma interleukin-6 (IL-6) and tumor necrosis factor-α (TNF-α) levels in plasma after intestinal IRI." (PMID 26497763, 2015). "This pathway promotes the pro-inflammatory production of other cytokines, such as IL-6 enhancing kidney damage in MM." (PMID 25386176, 2014).
kidney damage (continued). "However, the lack of complementary kidney function assessments (e.g., eGFR and imaging) and inflammatory markers (e.g., CRP and IL-6) limits our ability to definitively attribute these findings to nephropathy or systemic inflammation." (PMID 40177219, 2025). "For example, NF-κB is a pleiotropic transcription factor that regulates the expression of many genes involved in the inflammatory response during kidney injury and induces the release of proinflammatory cytokines such as TNF-α, IL-6, and IL-1β, which exacerbate kidney damage." (PMID 40607026, 2025). "Additionally, 5-FU triggered crosstalk between Nrf2 and NF-κB/p38MAPK axis by significantly upregulating p-p38, p-JNK, p-ERK1/2, p-NF-κB, TNF-α, IL-1β, TGF-β, and IL-6, while downregulating Nrf2 and HO-1, resulting in kidney damage." (PMID 40492124, 2025). "IL6 plays a crucial role in the development of CDDP-mediated kidney damage." (PMID 40573232, 2025). "In addition to IL6 and IL8, clinical studies revealed the association between TGF-β1 and nephropathy in T2D." (PMID 38541912, 2024). "Although a wide variety of kidney diseases have been reported as kidney involvement in MCD, we focused on the fact that IL-6 is the cause of nephropathy in MCD and searched the literature for cases of nephropathy in MCD that were successfully treated with tocilizumab." (PMID 39776937, 2024). "The invasion of immune cells might be provoked by IL-6 release from injured kidney cells, followed by mutual paracrine stimulation of proinflammatory cytokine release promoting kidney damage and fibrosis." (PMID 39723211, 2024). "Therefore, the present study was designed to evaluate the nephroprotective effect of diosmin against cisplatin-induced kidney damage by modulating IL-1β, IL-6, TNFα and renal oxidative damage in rats." (PMID 36770968, 2023). "In addition, ET combined with O increased the urea concentration (but still within the normal range) and, in the kidneys, increased the IL-6 concentration and reduced catalase, in addition to preventing the increase in the degree of kidney damage." (PMID 35657982, 2022). "In addition, the increased expression of angiopoietin 2, interleukin-6, tumor necrosis factor-α, and endostatin in the blood indicated kidney damage in this model." (PMID 36289909, 2022). "High fluid administration was associated with higher kidney damage score and IL-6 expression, independent of the rate of PEEP decrease." (PMID 34330283, 2021). "Furthermore, the levels of TNF-α and IL-6 increased as nephropathy progressed, with median serum TNF-α levels of 13.49 pg/mL in the normoalbuminuric group, 15.22 pg/mL in the Micro-MA group, and 18.28 pg/mL in the Macro-MA group." (PMID 34663293, 2021). "B4 could suppress the expression of IL-6, IL-1β, and NFκB but had a negative effect on TNFα expression, indicating that the anti-inflammatory effects of B4 on adenine-induced kidney damage are related to IL-6 and IL-1β/NFκB signaling." (PMID 31275420, 2019). "TGFβ can also activate pro-inflammatory status, particularly in the presence of IL-6 which may contribute to the progression of nephropathy." (PMID 31388341, 2019). "In addition, in T2DM, the development of nephropathy is associated with the activation of CD8 + T cells and with the increase of interleukin-6 (IL-6), NLRP3 inflammasome, and TNFR1/2 (Tumor necrosis factor receptors 1 and 2)." (PMID 29633887, 2018). "There is no specific toxicological explanation for the DON-induced lowering of the DPA proportion, or fumonisin B1, as a DPA increasing factor, but DON has been published to be strongly related to interleukin-6 (IL-6) expression in nephropathy, which has been markedly suppressed by DPA." (PMID 29271890, 2017). "Urinary IL-6 levels showed a high positive correlation with protein quantity in the renal hematuria with proteinuria >1,000 mg/24 h group and the overall observation group, providing a reference for the diagnosis of kidney damage." (PMID 24137196, 2013).
kidney damage (continued). "Cytokines of the TNF family, TNF SNPs, IL-6 serum levels, and IL6 gene SNPs, as well as macrophage inhibiting factor (MIF) and MIF gene variants, might play a role in favoring kidney damage and have been studied." (PMID 35205271, 2022). "However, IL-6 expression was decreased in the kidney, similar to the observation for IL-1β; this may also help alleviate kidney damage." (PMID 33647718, 2021). "LPS-triggered AKI additionally elevated pro-inflammatory cytokines, such as IL-6, Ccl2, and TNFα, while Inhibiting antioxidant enzymes like GSH, SOD, and GPX, resulting in oxidative stress and kidney damage." (PMID 40225865, 2025). "Somewhat confusing is the fact that genetic IL-6 deletion protected against HgCl2-induced AKI and IgA-mediated kidney damage in mouse models." (PMID 39723211, 2024). "Novel kidney injury biomarkers (IL-6, IL-8, TNF-α, NGAL, KIM-1, MMP-9, and IL-18) were used in this investigation to assess kidney damage more accurately." (PMID 38420620, 2024). "If these nephropathies are related to MCD, they would be expected to improve with the IL-6 antagonist tocilizumab because IL-6 is thought to be responsible for the onset of the disease." (PMID 39776937, 2024). "Recent studies correlated the overexpression of pro-inflammatory (IL-1β, IL-6, TNF-α, and VEGF) and profibrotic genes (ICAM-1 and VCAM-1) with the appearance of nephropathies in diabetic patients." (PMID 36139749, 2022). "The blood levels of IL-6, TNF-α, and endostatin released by kidney damage increased with age, especially in KK-Ay/TaJcl mice when compared with the control." (PMID 36289909, 2022). "In rats, the elevated TNF-α, IL-6, and MCP-1 were restored within the normal range in fisetin-treated hyperuricemic nephropathy." (PMID 36552226, 2022). "The RAGE ligand HMGB1 also plays a causal role in renal inflammation by enhancing ERK1/2, TNF-α, interleukin (IL)-6, and MCP-1, leading to nephropathy and chronic kidney disease." (PMID 33568752, 2021). "Pro administration attenuated rI/R-induced kidney damage and renal TNF-α, IL-6, and CXCL-10 expression." (PMID 34111028, 2021). "Consistently, our previous studies also found an increase of various proinflammatory cytokines, including TNF-α, IL-1β, IL-17, and IL-6, in TCE-hypersensitivity induced kidney damage." (PMID 34393767, 2021). "Taken together, out results suggests an activation of TNF-α/IL6 inflammatory pathways in DPN, similar to those reported in retinopathy and nephropathy." (PMID 33868296, 2021). "Consistent with our results, previous studies showed that patients with SLE have elevated monocyte number compared to controls, that monocytes from SLE patients spontaneously produce IL-6, and that LPS and TLR4 responses play a role in kidney damage in SLE." (PMID 25485543, 2014). "Recently, it was demonstrated that elevated levels of IL-6, MIP-1β, and mostly KC in kidney extracts of C. albicans infected mice correlate with kidney damage." (PMID 21533108, 2011). "Therefore, in this study, we aimed to investigate the effects of calcitriol administration on key markers of kidney damage in patients with early DKD, focusing on podocyte injury (nephrin and podocin), tubular damage (KIM-1), and inflammation (IL-6)." (PMID 41145267, 2025). "Additionally, urinary IL-6, TWEAK and GDF15 correlated with kidney damage assessed by decreased eGFR, while urinary IL-17, IL-18, TWEAK and GDF15 correlated with kidney damage assessed as the magnitude of proteinuria." (PMID 39188767, 2024). "Relative expression of IL‐6, MCP‐1, IL‐1β, and TNF‐α mRNA were significantly increased in kidney tissue, AND the levels of IL‐1β and p‐p65 were increased in adriamycin‐induced nephropathy rats." (PMID 37382268, 2023).